CCR7 (C-C motif chemokine receptor 7)
Diseases named in the same sentence as CCR7 in open-access papers (continued):
Sharing a sentence is not in itself a finding about the gene and the disease.
melanoma (continued). "In mice, overexpression of CCR7 in B16 melanoma cells increased metastasis to the lymph node and neutralizing its ligand, CCL21, using a specific antibody blocked this metastatic process, highlighting the importance of this CCR7/CCL21 axis in the metastasis to the regional lymph node." (PMID 30420855, 2018). "Indeed, the ability to eliminate B16F10 tumors, a model for melanoma, in vivo upon vaccination with wild-type or Cav1−/− DCs decreases in the latter, pointing to defects in CCR7 chemokine receptor and probably integrin activation." (PMID 30425987, 2018). "Furthermore, CCR7 transcript levels in a cohort of melanoma patients correlated with survival, pointing to a potential role for CCR7-expressing cells, including cDC1, in anti-tumor immunity." (PMID 29429633, 2018). "These tumor-infiltrated LN also contained a population of highly cytotoxic CD56dimKIR+CCR7+ NK cells that may have prognostic potential for melanoma." (PMID 29276510, 2017). "Moreover, the receptors CXCR3, CXCR4, CCR7 and CCR10 have been implicated in the process of metastasis in melanoma, based on studies with animals." (PMID 24559071, 2014). "Likewise, stable expression of CCR7 in B16 melanoma cells resulted in a markedly increased lymph node metastasis as compared to empty vector transfected B16 melanoma cells." (PMID 23667660, 2013). "Interestingly, expression of CCR7 in B16 melanoma cells induces metastasis to the lymph nodes, while, as previously discussed, expression of CXCR4 in murine B16 cells increases metastasis to the lungs." (PMID 24259307, 2013). "Apart from its role in the dissemination of hematologic malignancies, CCR7 is responsible, at least in part, for the ganglionar dissemination of solid epithelial tumors including breast, colorectal, head and neck and gastric carcinomas as well as melanoma." (PMID 24305507, 2013). "Xenografts of CCR7 expressing melanoma cells were found to grow towards regions of implanted LECs." (PMID 22505936, 2012). "There is data that CCL21, which is secreted by endothelial cells lining lymphatic channels, may mediate metastasis though interaction with its receptor, CCR7, on melanoma cells." (PMID 24212610, 2010). "However, several recent studies have shown that Gal-9 can be involved in melanoma metastasis under specific conditions, and CCR7 is highly expressed in metastases from melanoma patients, where a subpopulation of CCR7+ melanoma cells was found to co-express PD-L1 and Gal-9." (PMID 38264357, 2023). "However, the exact mechanism of CCL21/CCR7 signalling axis-induced lymphatic metastasis in melanoma after PTX treatment remains unclear." (PMID 35280672, 2022). "CCR7 is more commonly associated with melanoma rather than non-melanoma skin cancers." (PMID 35203305, 2022). "Thus, inhibition of the CCL21/CCR7 axis may be used to counteract chemotherapy-induced metastasis, providing a novel strategy to improve chemotherapeutic treatment for melanoma." (PMID 35280672, 2022). "Metacluster C58748 represented CD4+CD45RO+ T cells that expressed CCR6, CCR7, CXCR3 and CXCR5 suggesting TFH cells in melanoma which exhibit elevated CEACAM1 levels in the context of treatment-resistant compared to treatment-naive disease." (PMID 38956268, 2024). "We have mentioned in the section 3.5, in melanoma model, NF-κB regulate the transcription factor IRF1,which is essential in the development of CCR7+DCs from cDC1s." (PMID 39493763, 2024). "Spatial correlation of CCR7+ DC and effector CD8+ T cell transcripts was also evident in human melanoma and breast tumours." (PMID 38267413, 2024). "The major chemokine/chemokine receptor interactions occurring in melanoma development and progression include the CXCR4/CXCR7/CXCL12, CXCR3/CXCL9,10,11, CXCR1,2/CXCL8, CCR2/CCL2, CCR4/CCL17,22, CCR5/CCL5, CCR7/CCL21 and CCR10/CCL27 axes." (PMID 37170733, 2023).
melanoma (continued). "Regarding chemokine receptors, FGFR Mut melanoma expressed higher levels of CCR5, CCR7, CXCR3, CXCR4 and CXCR6 than their wild-type counterparts, but no statistical difference was observed (all P > 0.05)." (PMID 36426352, 2022). "CCR7 mediates lymphocyte migration, and CCR9 is involved in rare metastases to the small intestine in melanoma." (PMID 36092920, 2022). "Both treatments, singly or combined, increased expression of CCR7 and CXCR4 in melanoma cell lines, which, despite resulting in inhibition of cell growth, led to enhanced migration towards ligands." (PMID 35203305, 2022). "In CCR7-expressing melanoma cells, VEGF-C and CCL21 were expressed by lymphatic vessels and enhanced lymph node metastasis compared to non-CCR7-expressing control tumors." (PMID 35203305, 2022). "More recently, using the B16 melanoma model, VEGF-C-induced CCL21/CCR7-mediated lymphangiogenesis that promoted the entry of naïve T cells into melanomas and thereby, enhanced the activity of immunotherapy." (PMID 35203305, 2022). "In an immunocompetent melanoma mouse model, CD103+CD141+ cDC1 that carry TAA migrate to draining lymph nodes (dLN) in a C-C motif chemokine receptor 7 (CCR7)-dependent manner and present TAA to naïve CD8+ T cells residing in dLN, leading to T cell priming." (PMID 34359674, 2021). "For example, malignant melanomas express higher levels of CXCL1, CXCL2, and CXCL8 and receptors CXCR1, CXCR4, CCR10, and CCR7 compared with benign naevi." (PMID 34830780, 2021). "CC chemokine receptor 7 (CCR7) and CXC chemokine receptor 4 (CXCR4) are epigenetically upregulated in melanoma cells, and have the ability to induce metastasis of melanoma." (PMID 34198989, 2021). "In the lymph nodes, CCR7+ melanomas colonize and inhibiting the CCL21 with neutralizing antibodies blocks CCR7 mediated metastases." (PMID 33414786, 2020). "A previous study has shown that CD56dim CD57lo CD69+ CCR7+ KIR+ NK cells expand in tumor-infiltrated lymph nodes and display enhanced cytotoxic activity against autologous melanoma cells." (PMID 30761123, 2019). "These CD56low (CD57+CD69+CCR7+KIR+) NK cells were highly cytotoxic against autologous melanoma cells, and, in accordance with their homing into TILN, they expressed CCR7." (PMID 28360915, 2017). "We have evaluated, using flow cytometry, the expression of the chemokine receptors CXCR4, CXCR3, CXCR7, CCR7 and CCR10, at cell surface and intracellular levels, for thirteen human melanoma cell lines." (PMID 24559071, 2014). "Recently, immunohistochemical expression of CXCR4, CCR7 and CCR10 and their ligands has been described in tumor cells from primary and metastatic melanomas." (PMID 24559071, 2014). "Blood samples from patients with metastatic carcinoma (MC) or melanoma (MM) were enriched for CTC and expression of CR (CXCR4, CCR6, CCR7 and CCR9) was evaluated by flow cytometry." (PMID 22433180, 2012). "The mechanisms by which chemokine receptors on tumor cells facilitate LN metastasis are illustrated by studies on the roles of CCR7 and CCR10 in experimental metastasis of B16 murine melanoma cells." (PMID 24212647, 2011). "CCR7-positive B cells exhibited activation of the NF-κB pathway and demonstrated prognostic significance independent of the melanoma primary site or histologic subtype." (PMID 41758825, 2026). "The development of CCR7+DCs from cDC1s is dependent on transcription factor IFN regulatory factor 1 (IRF1), which is proved to be regulated by NF-κB in the maturation of tumor infiltrating cDC1s in melanoma model." (PMID 39493763, 2024). "Despite the correlation of the CCR7/CCL21 axis with melanoma metastasis to the lymph nodes, there are currently no inhibitors on the market to inhibit the downstream effects of this axis." (PMID 37170733, 2023).
melanoma (continued). "Treg signature genes CXCR5, TNFRSF9, CCR7, STAT1, GBP4, and EOMES were significantly upregulated in the young cohort and were correlated with higher survival in melanoma, while ID3, IL-17A, IL-17F, RDH10 and IL-11 were significantly upregulated in the old cohort." (PMID 36135194, 2022). "Overexpression of CCR7 in non-metastatic melanoma cell lines led to these cells migrating towards lymphatic endothelial cells." (PMID 35203305, 2022). "The overall survival rate of patients with high expressions of CCR7, CXCR5, EOMES, GBP4, TNFRSF9 and STAT1 in melanoma was significantly higher, which is consistent with the significantly higher survival rate observed for the young cohort receiving immunotherapy." (PMID 36135194, 2022). "Moreover, there was a significant 1,9-fold increase in the expression levels of CCR7 when the mean fluorescence intensity (MFI) was evaluated in HP-stimulated cells and AM derived from the monocytes of at least three different melanoma patients." (PMID 35805888, 2022). "The combination therapy of PTX and CCR7 mAb could simultaneously delay the tumour growth and reduce the lymphatic metastasis of B16F10 melanoma after PTX treatment." (PMID 35280672, 2022). "Interestingly, in melanoma clinical datasets, PAK4 expression levels negatively correlate with the presence of CCL21, the ligand for CCR7 expressed in CD103+ DCs." (PMID 36588582, 2022). "For instance, when melanoma cells express the receptor CCR7, they are able to migrate along the same ligand gradients as circulating immune cells to enter lymph nodes; however, when CCL21 is expressed by melanoma, immune cell recruitment to the TME via CCL21 gradients is magnified." (PMID 34830780, 2021). "In melanoma patients, cDC1s in the TME express high levels of CCR7, which predict T cell infiltration and improves clinical outcome, underscoring the importance of CCR7 expressing cDC1s for antigen trafficking and T cell priming." (PMID 33679726, 2020). "The machinery driving the colonization by melanoma cells of metastatic sites, including the bone, has been poorly investigated although previous studies correlated the CXCR3, CXCR4, CCR7 and CCR10 expression with the enhanced propensity to migrate to lymph nodes, lung and skin." (PMID 31324252, 2019). "Importantly, CCR7 selection either prior to, or post expansion led to a decrease in cytotoxicity of TCR-transduced T cells upon incubation with target melanoma cells." (PMID 28239467, 2017). "Tumors showing de novo expression of CCR7 in a murine isograft system (B16F10 melanoma bearing animals) showed lymph node metastases, whereas lung metastases were formed in the absence of CCR7 expression." (PMID 26320180, 2015). "Likewise, clear correlation was shown between CCR7 expression and lymph node metastasis formation via lymphatic vessels in case of head and neck cancers, NSCLC and melanoma." (PMID 26320180, 2015). "In this study we have analyzed, using flow cytometry, the systems formed by the chemokine receptors CXCR3, CXCR4, CXCR7, CCR7 and CCR10 and their ligands in thirteen human melanoma cell lines (five established from primary tumors and eight established from metastasis from different tissues)." (PMID 24559071, 2014). "Expression of CCR7 in a non-metastatic B16 melanoma cell line also increases metastasis to the lymph nodes." (PMID 24259307, 2013). "Studies show that malignant melanoma expresses high levels of CCR10 in addition to CXCR4 and CCR7." (PMID 24259307, 2013). "These chemokines, such as CCL21 are used by receptor expressing tumour cells (CCR7 for instance is upregulated in metastatic but not non metastatic melanoma cells) and provide a route out of the primary melanoma to the lymph node." (PMID 20478045, 2010).
melanoma (continued). "Distinct immune signatures, such as CD8+PD-1+ T cells, CD8+ effector memory (CD8+CD45RA−CD45RO+CCR7−) T cells, activated CD4+ T cells (CD4+CD38+HLA-DR+), and NK cells (CD16+CD56+CD38+HLA-DR+) showed the treatment response and immune-related adverse events in melanoma patients in ICI therapy." (PMID 36569825, 2022). "When model mice with GBM and melanoma overexpressed VEGF-C, the anti-PD-1/CTLA-4 combination treatment showed a good effect, which was abolished when CCL21/CCR7 blockaded, suggesting an augmented effect of VEGF-C on checkpoint treatment via the CCL21/CCR7 pathway." (PMID 35359624, 2022). "Importantly, combination of PTX and CCR7 mAb could simultaneously delay the tumour growth and reduce the lymphatic metastasis in B16F10 melanoma." (PMID 35280672, 2022). "This bowel injury allowed the recruitment, activation, and mobilization of CCR7-expressing dendritic cells to Peyer patches, mLN, and tdLN, culminating in the massive infiltration of IFNγ-producing CD4+ and CD8+ TILs and tumor control of poorly immunogenic melanoma." (PMID 33262469, 2021). "In addition, the modulation of the frequency of T cell subpopulations, in particular, activated central memory or effector memory T cells (CCR7+CD45RA− or CCR7−CD45RA−), has been investigated as a correlative biomarker for immune checkpoint infusions in melanoma patients." (PMID 30004433, 2018). "Interestingly, only metastatic malignant melanoma cells express CCR7, while their nonmalignant counterparts do not." (PMID 22505936, 2012). "Furthermore, our results demonstrated that PTX could not upregulate the expression of CCR7 in B16F1 melanoma cells." (PMID 35280672, 2022). "Immunohistochemical analysis of chemokine receptor expression patterns in non-melanoma skin cancer demonstrated downregulation of CCR6 and upregulation of CCR7 and CXCR4 in potentially metastatic non-melanoma skin cancer." (PMID 35203305, 2022). "For instance, Chemotrap-1 is a soluble macromolecule not related to CCR7, but that binds CCL21 with high affinity and prevents the metastatic extension of melanoma in animals." (PMID 24068998, 2013).
COVID-19 (57 papers, 2020 to 2026). A disease caused by infection with severe acute respiratory syndrome coronavirus 2. "CCR7 expression varies in peripheral blood mononuclear cells during different stages of COVID-19, underlining the complexity of the immune responses." (PMID 38474155, 2024). "Further, we observed that the proportion of CCR7+ Tregs in COVID-19 patients was lower than that in the healthy controls and decreased as the severity of the disease worsened." (PMID 40114921, 2025). "Increased expression of chemokine and cytokine receptors such as CXCR5, CCR4, CCR5, and CCR7 has been reported in both active and recovered COVID-19 individuals." (PMID 38357647, 2024). "The relationship between CCR7 and COVID-19 in AT complements existing research focused on blood cells." (PMID 38474155, 2024). "High levels of CCL21 are associated with persisting pulmonary impairment post-COVID-19 hospital admission, and CCL21 is recognized for its involvement in recruiting CCR7+ T cells to secondary lymphoid organs, orchestrating the adaptive immune response." (PMID 38474155, 2024). "Next, we aimed to further characterize the hematopoietic cells expressing CCR7 within COVID-19 lungs." (PMID 36774347, 2023). "We show here that myofibroblasts in COVID-19 lungs also express CCR7 and, thus, can respond to the elevated CCL21 signals within the adventitial niches, particularly in the prolonged disease phase." (PMID 36774347, 2023). "The peripheral immune response in patients with CAP was highly similar to that in patients with COVID-19, but increased CCR7 expression on classical monocytes was only present in CAP." (PMID 38077404, 2023). "Further, chemokine and cytokine receptors (CXCR3, CXCR4, CXCR5, CCR4, CCR5, and CCR7) expression was increased in active COVID-19 and recovered patients." (PMID 36532041, 2022). "The memory status of COVID-19 patients showed a significantly decreased median in the proportion of central memory (CM, CCR7+/CD45RA-) CD8+ T-cells compared to healthy controls: 8.3% (5.1–11.2) vs. 13.7% (8.4–18.7) (p < 0.001)." (PMID 35203509, 2022). "On the other hand, COVID-19 convalescents vs. control subjects were found to sustain elevated levels of effector memory CD3+CD8+CD45RO+CCR7– CD8+ T cells." (PMID 36146713, 2022). "In moderate patients, there were all three subgroups up-represented, while the naïve group (CCR7+SELL+) decreased in severe COVID-19 patients." (PMID 35159352, 2022). "COVID-19 is characterized by the activation of a subset of cTfh cells with reduced CCR7 expression, high expression of PD-1 and high expression of ICOS-1 expression, which remains active for up to two weeks after symptoms occur." (PMID 36034704, 2022). "Lower circulating CD27+CD28+CD45RA+CCR7+ ‘naïve’ CD4+ T cell counts predicted a poor prognosis in patients with acute COVID-19." (PMID 35632823, 2022). "In natural infection, long-lasting SARS-CoV-2-specific memory T cells observed in convalescent COVID-19 patients displayed a phenotype of central memory CD4+ T cells (CD4+CCR7+CD45RA-) or stem cell-like memory CD4+ T cells (CD4+CCR7+CD45RA+)." (PMID 35309363, 2022). "Six hub genes (FCGR3A, CD69, IFNG, CCR7, CCL5, and CCL4) were closely associated with COVID-19 and HF." (PMID 36420258, 2022). "We and others have also suggested the generation of SARS-CoV-2-specific TSCM cells in the convalescent phase of COVID-19 on the basis of the expression of CCR7 and CD45RA8,23." (PMID 34193870, 2021). "A recent study has reported a relative loss of peripheral blood CD45RA+CD27+CCR7+CD95− naïve CD4 T cells compared with the controls, but increased CD45RA−CD27−CCR7+ EM2 and CD45RA+CD27−CCR7− EMRA cells in patients with COVID-19 compared to the healthy donors." (PMID 34696395, 2021). "In leukocytes from whole blood, CCR7 regulation during COVID-19 exhibits heterogeneous findings." (PMID 38474155, 2024). "ILCps in COVID-19 patients upregulated CCR7 gene expression compared with controls." (PMID 39026668, 2024).